MPZL2 (myelin protein zero like 2)
Description:
Mediates homophilic cell-cell adhesion.
Synonyms: EVA; EVA1; DFNB111
Tractability: Antibody: UniProt predicts a signal peptide or a membrane-spanning region; its Gene Ontology location is reachable by antibodies, with medium confidence. PROTAC: ubiquitination databases record sites on it.
Gene: Protein-coding gene on chromosome 11 (118,253,416 to 118,264,536, reverse strand). Ensembl gene ENSG00000149573.
Subcellular location: Membrane
Subcellular location (Human Protein Atlas): Cell Junctions
Gene Ontology:
Molecular function: protein binding
Biological process: anatomical structure morphogenesis; cell-cell adhesion; homophilic cell-cell adhesion
Cellular component: cytoskeleton; plasma membrane; membrane
Genetic constraint (gnomAD): Loss-of-function variants: 29 observed, 23.06 expected, observed/expected ratio (o/e) 1.26, 90% interval 0.94 to 1.7. The upper end of that interval is the gene's LOEUF score, 1.7, which puts it in group 6 of 6, group 1 being the genes least tolerant of losing a copy. Missense variants: 286 observed, 268.32 expected, observed/expected ratio (o/e) 1.07, 90% interval 0.97 to 1.18. Synonymous variants: 81 observed, 96 expected, observed/expected ratio (o/e) 0.84, 90% interval 0.7 to 1.01.
Gene-disease validity (ClinGen):
ClinGen rates the evidence that MPZL2 causes each of these diseases.
nonsyndromic genetic hearing loss (autosomal recessive): Strong.
Homologues: Orthologues: chimpanzee MPZL2 (99% identical), macaque MPZL2 (99% identical), pig MPZL2 (93% identical), dog MPZL2 (89% identical), rabbit MPZL2 (88% identical), rat Mpzl2 (82% identical), mouse Mpzl2 (81% identical), tropical clawed frog mpzl2 (45% identical), zebrafish mpzl2b (35% identical). Paralogues in human: MPZL1 (28% identical), MPZL3 (26% identical), SCN2B (25% identical), JAML (23% identical), MPZ (23% identical), SCN4B (23% identical).
Diseases named in the same sentence as MPZL2 in open-access papers:
MPZL2 is named in the same sentence as 29 diseases in open-access papers, as found by Europe PMC text mining. Sharing a sentence is not in itself a finding about the gene and the disease. The quoted sentences say what the papers report.
hearing loss (7 papers, 2021 to 2025). "Apart from symmetrical and moderate sensorineural hearing loss, the MPZL2-related phenotype was characterized by progressive hearing loss with variation in the onset age (congenital defect to onset at the young adult stage)." (PMID 38254107, 2024). "This was the first reported case of mild-to-moderate hearing loss caused by MPZL2 variants in China." (PMID 36568381, 2022). "MPZL2 (myelin protein zero-like protein 2) is a transmembrane glycoprotein with genomic variants associated with hearing loss." (PMID 35584218, 2022). "Additionally, MPZL2 in category 4,62SLC26A4 in category 5,63 and mitochondrial machinery-related genes in category 764,65,66 are associated with progressive hearing loss in the previous studies." (PMID 40592345, 2025). "Eight pedigrees with homozygous or compound heterozygous variants of MPZL2 from a hearing loss patient cohort of 3272 who underwent genetic testing from December 2015 to November 2022 in the Genetic Testing Center of Chinese PLA General Hospital, were included in this study." (PMID 38254107, 2024). "We determined that in the Chinese population, the genetic load of MPZL2 defects was 0.24% (8/3272) in patients diagnosed with hearing loss and 7.02% (8/114) in patients diagnosed with hereditary moderate sensorineural hearing loss caused by STRC, OTOA, OTOG, OTOGL, TECTA, MPZL2 and others." (PMID 38254107, 2024). "A LoF variant in the adhesion protein MPZL2 (MPZL2c.72delA) was previously associated with hearing loss, and we identified a 100KGP patient with additional nervous system, cardiovascular, and kidney defects, thus extending the phenotypic spectrum of MPZL2c.72delA." (PMID 35584218, 2022). "Mutations in MPZL2, the characteristic genetic etiology of autosomal recessive deafness loci 111 (DFNB111), cause non-syndromic and moderate sensorineural hearing loss." (PMID 38254107, 2024).
deafness (6 papers, 2020 to 2025). An inherited or acquired condition characterized by the complete loss of the ability to hear from one or both ears. "In addition, we identified potentially novel deafness-associated genes Mpzl2 in IMCs and Tbx1 in MCs along with the known deafness-associated genes in IMCs (Kcnj10, Met, Mitf, Gjb6, Ednrb, and Gjb2) and in MCs (Kcnq1, Esrrb, Kcne1, Lrp2, Slc22a4, and Hgf)." (PMID 37322474, 2023). "In this study, by analyzing the genetic data of 3272 Chinese patients with HL, we determined the correlation between MPZL2 defects and deafness, especially in those with mild-to-moderate HL." (PMID 38254107, 2024).
breast carcinoma (4 papers, 2016 to 2025). "A closely related homolog of MPZL3, MPZL2 (EVA1) localizes with E-cadherin and ZO-1 at cell–cell junctions in breast cancer epithelial cells." (PMID 40631617, 2025). "MPZL2 expression is significantly decreased in breast carcinoma cells growth-arrested by siRNA knockdown of the migration and invasion regulatory PACE4 proprotein convertase." (PMID 27144453, 2016). "MPZL2 has been observed in cell growth, invasion and adhesion of breast cancer cells." (PMID 34062972, 2021).
glioblastoma (2 papers, 2020 to 2025). The most malignant astrocytic tumor (WHO grade IV). "MPZL2 was found to maintain the pluripotency and self-renewal of glioblastoma-initiating cells." (PMID 32111240, 2020).
autosomal recessive deafness-111 (1 paper, 2024). "Genetic defects in MPZL2 were determined to be the cause of autosomal recessive deafness-111 (DFNB111, MIM: 618145) with non-syndromic, early-onset, symmetrical and moderate sensorineural HL, which was first identified by Wesdorp in 2018." (PMID 38254107, 2024).
gastric cancer (1 paper, 2021). A primary or metastatic malignant neoplasm involving the stomach. "For example, expression of CDKN1C, RASSF7, GPRC5A, and MPZL2 were all significantly related to KLF5 in gastric cancer tissue." (PMID 33923166, 2021).
leukemia (1 paper, 2025). A malignant (clonal) hematologic disorder, involving hematopoietic stem cells and characterized by the presence of primitive or atypical myeloid or lymphoid cells in the bone marrow and the blood. "Similarly, several genes adjacent to DMRs in our dataset represent canine homologs of human cancer-associated genes: TNFSF13 is known to be related to tumor cell proliferation in human studies, while RUNXs and MPZL2 are associated with leukemia in human." (PMID 41468414, 2025).
lung adenocarcinoma (1 paper, 2024). A carcinoma that arises from the lung and is characterized by the presence of malignant glandular epithelial cells. "There were 5 genes with a causal relationship to lung adenocarcinoma, including RNASET2, MPZL2, MPZL3, CHRNA5 and UCKL1." (PMID 38834983, 2024).
psoriasis (1 paper, 2011). An autoimmune condition characterized by red, well-delineated plaques with silvery scales that are usually on the extensor surfaces and scalp. "In all five mouse phenotypes, there was increased expression of S100a9, Lcn2, S100a8, Sprr1b, Mpzl2, Has3, as well as decreased expression of Tppp, Stxbp6, and Cldn23, and each of these effects is consistent with characteristic expression patterns in clinical psoriasis." (PMID 21483750, 2011).
MPZL2 also shares sentences with these, for which no sentence is quoted: tumor (8 papers); cancer (2); auditory neuropathy spectrum disorder (1); breast tumors (1); Cachexia (1); cervical tumors (1); citrullinemia (1); diabetes (1); Down syndrome (1); gynecologic cancers (1); Hearing impairment (1); Hyperglycemia (1); kidney disease (1); Lissencephaly 5 (1); lung carcinoma (1); ovarian carcinoma (1); pancreatic ductal adenocarcinoma (1); Schwartz-Jampel syndrome (1); tauopathy (1); Visual impairment (1).